CXCL12 (C-X-C motif chemokine ligand 12)
Diseases named in the same sentence as CXCL12 in open-access papers (continued):
Sharing a sentence is not in itself a finding about the gene and the disease.
breast carcinoma (continued). "RNA gene expression results from our novel immune competent breast cancer model provides several molecular indicators such as TNC and CXCL12 to direct a future combined “TIL‐matrix‐release‐and‐reactivate” strategy for improving ICT in breast cancer." (PMID 33988305, 2021). "We demonstrate here that the CXCR4 and CCR7 receptor ligands, CXCL12 and CCL19, cooperatively bind and selectively elicit synergistic signalling responses in invasive breast cancer cell lines as well as primary mammary human tumour cells." (PMID 34685420, 2021). "Studies have found that BRIP1 can promote the invasion of breast cancer (BC) cells by regulating the expression of multiple downstream target genes, such as MGAT5, EPCAM, and CXCL12, especially in the triple-negative phenotype MDA-MB-231 cell line." (PMID 34408776, 2021). "The chemokine CXCL12 and its receptor, CXCR4 and CXCR7, play an important role in breast cancer growth and metastasis." (PMID 35111484, 2021). "Tumor cells, dendritic cells, and macrophages in the breast cancer environment secrete chemokines such as CCL5, CCL17, CCL22, and CXCL12, which attract peripheral regulatory T cells (Tregs)." (PMID 34034721, 2021). "In summary, WWP1 govern CXCL12-mediated lysosomal degradation of CXCR4, leading to regulation of cell migration and bone metastasis in breast cancer." (PMID 34226507, 2021). "WWP1 inhibited CXCL12-induced cell migration and bone metastasis in breast cancer, while knockdown of WWP1 promoted bond metastasis of breast cancer cells." (PMID 34226507, 2021). "Examples of this include, the bioactive lipid, lysophosphatidic acid, and its receptor, LPAR-1 in breast cancer, chemokines, CXCL8/IL8 and CXCR1 and CXCR2 in melanoma, pancreatic cancer and gastric tumors and CXCL12 and CXCR4 in multiple cancers." (PMID 33329395, 2020). "In breast cancer, CXCR4 promotes metastasis to organs like bone, liver, and lung, sites commonly affected by metastatic breast cancer, where its ligand, C-X-C motif chemokine 12 (CXCL12), is expressed in large quantities." (PMID 32075106, 2020). "Human breast cancer cells express more CXCR4/RANK than normal epithelial cells, and CXCL12, the receptor of CXCR4, is highly expressed in the liver, lung, and bone marrow." (PMID 32117996, 2020). "The results indicated that the expression levels of CXCL9, CXCL10, CXCL11, and CXCL13 were marked higher in breast cancer tissues than in normal tissues, while the expression levels of CXCL1, CXCL2, CXCL3, and CXCL12 were lower inversely." (PMID 32963527, 2020). "High levels of CXCL12 and CXCL16 in CAFs from human brain cancer metastasis attract breast cancer cells via the CXCR4-CXCL12 and CXCR6-CXCL16 pathways." (PMID 33096815, 2020). "In breast cancer, the CXCL12/CXCR4 axis plays a crucial role in directing the metastasis of CXCR4-positive cancer cells to organs that express high CXCL12 levels, such as the lungs, bone marrow, and lymph nodes." (PMID 32498358, 2020). "Another study found that CXCL12/CXCR4 signal axis activated HER2 through SRC, promoting the growth and proliferation of breast cancer cells, so that MCF‐7 cells have resistance to tamoxifen." (PMID 32253815, 2020). "Since the recruitment of T-regs into the TME occurs partly via the C-X-C motif chemokine-12 (CXCL12) signaling factor, it would be interesting to see if TME in breast cancers from AA compared to EA patients produces more CXCL12." (PMID 32714862, 2020). "Angiopoietin-like protein 2, secreted by breast cancer cells, increases CXCR4 expression in breast cancer, which increases cross-talk between CXCR4 and CXCL12 and, as a result, recruits breast cancer cells to the bone metastatic site." (PMID 32674405, 2020). "In breast cancer, based on the tumor type, MDSCs are recruited to the tumor sites by various chemokines including CCL2, CXCL5, and CXCL12 (SDF-1)." (PMID 32726950, 2020).
breast carcinoma (continued). "Metastatic breast cancer cells express high levels of CXCR4 and stromal cells in distant organs express high levels of CXCL12, the CXCR4 ligand." (PMID 32079335, 2020). "The corresponding ligands CXCL12 and CCL21 are present at elevated levels in lymph nodes, lung, liver and bone marrow—preferred distant metastatic sites of breast cancer." (PMID 32547940, 2020). "In breast cancer, CXCR4 is overexpressed and is responsible for metastasis to predilection sites in the body that are enriched for CXCL12 including the lungs, bone marrow and brain." (PMID 32872485, 2020). "When combined with eribulin, a chemotherapeutic microtubule inhibitor, a novel CXCL12/CXCR4 antagonist POL5551 reduces metastasis and prolongs survival in mice after resection of the primary breast cancer, compared with single-agent eribulin." (PMID 33123472, 2020). "Breast cancer cells expressing ACKR3 internalize and degrade CXCL12 leading to its removal from the environment and to decreased CXCR4 signaling." (PMID 33096815, 2020). "The involvement of CXCL12/CXCR4 axis is well known in metastatic spreading, drug resistance, and overall worse diagnosis in breast carcinoma." (PMID 31652624, 2019). "Particularly, chemokines and chemokine receptors such as CXCL12/CXCR4-CXCR7, CXCL16/CXCR6, CCL25/CCR9, CCL2/CCR2, and CCL5/CCR5 are found to play a crucial part in breast cancer progression." (PMID 31652624, 2019). "NR2F1 provokes a reduction in chemokine CXCL12 expression and enhancement of CXCR4 expression, and it stimulates breast cancer cell migration." (PMID 31146704, 2019). "The corresponding ligands on the other hand, CXCL12 and CCL21, are present at elevated levels in lymph nodes, lung, liver, and bone marrow—preferred distant metastatic sites of breast cancer." (PMID 31533220, 2019). "CXCL12 is a chemokine and via the CXCR4/CXCL12 axis of breast cancer cells induces a chemotactic response and invasion." (PMID 31341222, 2019). "C-X-C motif chemokine 12 (CXCL12) secreted by CAFs can also induce EMT in oral squamous cell carcinoma and breast cancer models." (PMID 31640297, 2019). "The process of migration and invasion are an important step in the metastasis of breast cancer, and these processes can be regulated by a variety of factors such as BRMS1, E-cadherin, CXCL12, MMP9, Orai1, Stim1, TGF-β, and VEGF." (PMID 29316690, 2018). "Upon binding with the chemokine CXCL12, the chemokine receptor CXCR4 has been shown to promote breast cancer progression." (PMID 30441765, 2018). "Employing orthotopic mammary carcinoma models in a standard readout for the assessment of CSC content, we uncovered an important role of the CXCL12/CXCR4 axis during the early engraftment phase." (PMID 29632733, 2018). "Of clinical interest, CXCL12/CXCR4 levels are increased in many cancers, including breast cancer, pancreatic cancer, oral squamous cell carcinoma, ovarian cancer, cervical carcinoma, and gastric cancer." (PMID 30420856, 2018). "Testosterone treatment induces both CXCL12 and CXCR4 expression in ER+ve breast cancer cells but only if AR and SRC1 are co-expressed." (PMID 30416486, 2018). "ACKR3, also known as CXCR7, is another atypical receptor binding CXCL12 and CXCL11, and has been shown to regulate breast cancer metastases." (PMID 30591657, 2018). "Prior to screening in both Jurkat and breast cancer cells, two assays were used to characterize their interaction with CXCR4: (i) CXCL12 induced calcium flux; and (ii) the HIV-1IIIB MAGI entry assay." (PMID 29682200, 2018). "Although our findings will require a deeper insight into the regulatory pathways involved in the CXCR4/CXCL12 axis, the present study highlights the axis as an important target for future therapy in FMC as it has been proved to be in human breast cancer." (PMID 30012106, 2018). "CXCL12, also known as stromal cell–derived factor-1 (SDF-1α), binds to CXCR4, which is often overexpressed in breast cancer and has been correlated with poor clinical outcome." (PMID 28415580, 2017).
breast carcinoma (continued). "We recently reported that E2 controls the activity of the CXCL12/CXCR4/CXCR7 signaling axis in breast tumor cells and influences the proliferation and migration of breast cancer cells." (PMID 28666461, 2017). "CXCL12 induction of STAT3 phosphorylation has also been reported in other types of cancers, such as bladder cancer, breast cancer, and small cell lung cancer." (PMID 29379494, 2017). "To further investigate the importance of chemokines CXCL12 and CXCL16 secreted by metastatic CAFs on breast cancer cell migration, we analyzed the expression of cognate chemokine receptors CXCR4 and CXCR6 on patient-derived cancer cells." (PMID 28649646, 2017). "Recently, CXCL12 (stromal cell-derived factor-1, SDF-1)/CXCR4 system has been reported to be involved the establishment of LN metastasis in different cancers, e.g., breast cancer and SCC, and ovarian cancer." (PMID 28036019, 2016). "This activation causes an increased CXCR4 expression and subsequent feed-forward activation of FAK, resulting in CXCR4/CXCL12-dependent increase in migration, invasion, TEM and metastasis of breast cancer cells." (PMID 26993780, 2016). "Namely, breast cancer cells that express CXCR4 frequently metastasize to the lung, liver, lymph node and bone marrow where CXCL12 is expressed at high levels." (PMID 27136535, 2016). "When an inhibitory factor for BMP-4 was added to the co-cultures, migration of breast cancer cells was decreased and their CXCR-4 expression downregulated, demonstrating that BMP-4 acted as an activator of the CXCR-4/CXCL-12 pathway." (PMID 27571063, 2016). "The heat-sensitive chemokines CXCL12 and MIF, both known to promote breast cancer metastasis, showed the highest fold change in secretion by irradiated lung epithelial cells compared to control, which was confirmed in our study." (PMID 26396176, 2015). "Furthermore, assessment of gene expression or intracellular cytoplasmic CXCR4 detection by flow cytometry could complement the analysis by IHC and indicate how CXCR4 and CXCL12 are behaving at the molecular level, deciphering the interface of this axis in the breast cancer pathobiology." (PMID 26161302, 2015). "The most studied role for CXCL12 chemokine and its receptor CXCR4 in breast cancer pathogenesis is the metastasis event, although several reports have demonstrated its involvement in other processes, such as angiogenesis and tumor growth." (PMID 26161302, 2015). "One of the key points on describing the role of the CXCR4/CXCL12 axis in breast cancer pathogenesis is concerned with the IHC analysis of only CXCR4, once limited information on CXCL12 expression has been published." (PMID 26161302, 2015). "We selected the CXCL12 and MIF cytokines for further study because of a high fold change (more than 80-fold) and a known role in breast cancer metastasis." (PMID 26396176, 2015). "Once the cells arrive in the lung, increased levels of CXCL12 and MIF retain the breast cancer cells in lung and provides it with survival and growth factors, so metastatic growth is enhanced." (PMID 26396176, 2015). "It has also been reported that CXCL12/CXCR4 signaling induces actin polymerization and chemotactic property of breast cancer cells." (PMID 26055698, 2015). "In this respect, an elegant study demonstrated that CAFs localized in invasive human breast carcinomas promote tumor growth and angiogenesis through high level secretion of Stromal-Derived-factor-1 (SDF-1)/CXCL12." (PMID 25474039, 2015). "Of note, ACKR3 preferentially sequesters the monomeric form of CXCL12, whereas dimeric CXCL12 showed significantly lower binding to ACKR3 in vitro and in a breast cancer xenograft model." (PMID 26347749, 2015). "It is also used for a variety of disorders that depend on the interplay of CXCR4 with its agonist CXCL12 (also called: SDF-1) including leukemia and breast cancer." (PMID 27429863, 2015).
breast carcinoma (continued). "For example, fibroblast expression of stromal cell-derived factor-1 (SDF-1/ CXCL12) acts as a systemic chemotactic signal for circulating immature endothelial cells (ECs), leading to breast cancer vascularization and metastasis." (PMID 26075202, 2015). "The rate of breast cancer specific mortality was higher in patients with both high phosphorylated-CXCR4 expression and low plasma CXCL12 levels than either low plasma CXCL12 or high phosphorylated-CXCR4 expression alone." (PMID 26161302, 2015). "We here present evidence that GLI1 up-regulates the expression of CXCR4, CXCR7 as well as LCP1/L-PLASTIN, an actin-binding protein crucial for CXCL12/CXCR4 signaling, in breast cancer cells." (PMID 26413813, 2015). "In this context, it was recently demonstrated that violacein reduces the production of CXCL12 and its interaction with CXCR4 in a model of human breast cancer through the inhibition of matrix metalloproteinase-2/9 activity." (PMID 25938431, 2015). "The chemokine CXCL12 (stromal cell-derived factor-1, SDF-1) and its receptor CXCR4 play a major role in tumor initiation, promotion, progression and metastasis, especially for breast cancer cells." (PMID 24770893, 2014). "To gain a deeper insight into the role of it in breast cancer, we investigated the CXCL12 and CXCR4 expression in breast cancer cells MCF-7, MDA-MB-435s, and MDA-MB-231." (PMID 24810923, 2014). "The expression profiles of CXCR4, CXCR7, CXCL12, and COUP-TFI in breast cancer cells from patients exhibiting different tumor grades (82 breast tumors and control non-tumor samples) were measured using real-time PCR." (PMID 24906407, 2014). "CXCR4 is upregulated in metastatic breast cancer cell lines and lymph node metastasis, and cells expressing CXCR4 predominantly migrate to tissues that express the ligand CXCL12." (PMID 25254213, 2014). "In the present study, we developed MCF-7 breast cancer cells overexpressing COUP-TFI protein and examined the regulation of CXCL12 signaling axis." (PMID 24906407, 2014). "It suggested that the chemokine CXCL12 and its sole ligand CXCR4 played important role in the malignant of breast cancer." (PMID 24810923, 2014). "In the present study, we investigated CXCL12 and CXCR4 expression in breast cancer and further to analyze its role in survival and invasive ability of breast cancer cells." (PMID 24810923, 2014). "MCF-7 breast cancer cells overexpressing COUP-TFI and human breast tumors were used to investigate the role of COUP-TFI in the regulation of CXCL12/CXCR4 signaling axis in relation to cell growth and migration." (PMID 24906407, 2014). "CXCL12 itself stimulates the tumor growth directly, via the CXC-chemokine receptor 4 (CXCR4), expressed among others on human breast carcinoma cells." (PMID 25254213, 2014). "We elucidated CXCR7-mediated signaling pathways and showed that CXCL12 induced p44/p42 ERK and p-STAT3 in breast cancer cells." (PMID 24886617, 2014). "Our previous research indicated that co-expression of CXCR4 and CXCL12 was correlated with lymph node metastasis and TNM stage of breast cancer." (PMID 24810923, 2014). "The co-expression of CXCR4 and CXCL12 which correlated with lymph node metastasis and TNM stage of breast cancer also has a reasonable reason." (PMID 24810923, 2014). "It was identified that breast cancer cells express CXCR4 highly and that the ligand of CXCR4, CXCL12, is primarily expressed in the lungs, liver and bone marrow." (PMID 24932250, 2014). "Our results revealed the role of the CXCL12/CXCR7 axis in regulating cell migration and wound healing in breast cancer cells, which have been shown to play an important role in regulating breast cancer metastasis." (PMID 24886617, 2014). "Hence, CXCR4 and CXCL12 form an important signaling axis between tumor cells and the tumor microenvironment, with the interaction influencing the adhesion, migration and invasion of tumor cells, reflecting the strong association of CXCR4 with breast cancer metastasis." (PMID 24475985, 2014).
breast carcinoma (continued). "We previously showed that CXCL12 promotes amoeboid transitions through the formation of a complex between mDia2 and its functional inhibitor, DIP, in MDA-MB-231 breast cancer cells." (PMID 24587343, 2014). "Here, we report that the CXCL12/CXCR4 signaling pathway, a crucial pathway in cell growth and migration, is an endogenous target of COUP-TFI in breast cancer cells." (PMID 24906407, 2014). "It suggested that the chemokine CXCL12 and its sole ligand CXCR4 play important role in the malignance of breast cancer." (PMID 24810923, 2014). "Studies show that metastatic breast cancers selectively express CXCR4 and migrate to organs that express high levels of its respective ligand CXCL12, also known as SDF-1." (PMID 24259307, 2013). "The chemokine CXCL12/SDF-1 and its G-protein-coupled receptor CXCR4-mediated signaling pathways play important roles in the migration and invasion of breast cancer cells." (PMID 22295247, 2012). "The chemokine CXCL12 and its receptor CXCR4 play important roles in the colonization of human breast cancer cells to their metastatic target organs." (PMID 22253872, 2012). "We had previously reported that blocking the CXCR4/CXCL12 interaction with a peptidic CXCR4 antagonist, TN14003, suppresses lung metastasis in models of breast cancer and head and neck cancer." (PMID 22485156, 2012). "CXCL12 binds to the G protein-coupled receptor CXCR4, which is often overexpressed in breast cancer and has been correlated with poor clinical outcome." (PMID 22314082, 2012). "Further, their respective ligands CXCL12 and CCL21 are highly expressed in the target organs of breast cancer metastasis that can partly explain the metastatic pattern in breast cancer patients." (PMID 22481918, 2012). "Their respective ligands CXCL12/ SDF-1a and CCL21/6Ckine are highly expressed in organs representing the first destinations of breast cancer metastasis." (PMID 23905066, 2012). "Overexpression of CXCL12 increased in vitro invasion and migration of human breast cancer MDA-MB-231 cells, and overexpression of CXCL12 was seen in breast cancer patients with lymph node-positive metastatic disease with a poor prognosis." (PMID 22314082, 2012). "The positive regulation of CXCL12 and CXCR4, which can induce cell proliferation and survival, has been well correlated with the growth effect of E2 on breast cancer cells." (PMID 21695171, 2011). "Specific siRNAs directed against CXCL12, CXCR4 and CXCR7 were used to assess the importance of this axis in the basal and E2-dependent growth of breast cancer cells." (PMID 21695171, 2011). "Recent studies have indicated that the epigenetic mechanisms that negatively regulate the expression of CXCL12 and ESR1 are involved in breast cancer metastasis and correlate with poor survival of patients." (PMID 22220212, 2011). "CXCL12/CXCR4 signaling has been shown to stimulate the chemotactic and invasive behavior of breast cancer cells in vitro and in vivo, and has been proposed to serve as a homing mechanism for cancer cells to sites of metastasis." (PMID 22152016, 2011). "In this study, we examined the regulation of the CXCL12/CXCR4/CXCR7 axis and its involvement in the proliferation and survival of E2-dependent and -independent breast cancer cells." (PMID 21695171, 2011). "CXCL12 is the ligand for CXCR4 and is highly expressed in areas common for breast cancer metastasis, including the axillary lymph nodes." (PMID 22295222, 2011). "This study investigated the expression of CXCR4, CCR7, CXCL12, CCL21, and EGFR to illustrate the role of these biomarkers in breast cancer metastasis and prognosis." (PMID 20181250, 2010). "MCF7 breast cancer cells, previously shown to express CXCR7 and CXCL12, were used as a positive control." (PMID 20877573, 2010). "Malignant breast cancer cells express CXCR4, invade the extracellular matrix, and circulate in the blood and lymphatic vessels attracted by CXCL12 that is abundantly released by target metastatic organs." (PMID 20049170, 2010).